HLA-G (major histocompatibility complex, class I, G)
Diseases named in the same sentence as HLA-G in open-access papers (continued):
Sharing a sentence is not in itself a finding about the gene and the disease.
tumor (continued). "Our novel CAR-NK strategy exploits the dual nature of HLA-G as both a tumor-associated neoantigen and an ICP to counteract tumor spread." (PMID 34663641, 2021). "To date, little is known about the relationship between HLA-G expression and tumour-infiltrating immune cells in the tumor microenvironment, which dictate the functional orientation of associated immune checkpoints." (PMID 34276642, 2021). "The aim of this review was to obtain a complete and objective view on the current status of the relationship between tumour HLA-G expression and clinicopathological parameters, including clinical outcome, in carcinoma patients." (PMID 34361031, 2021). "The rate of HLA-G gene alteration was 1.6% in 10,953 patients and 10,967 tumor samples from cBioPortal." (PMID 34276642, 2021). "Tumour immune scores (IS) were generated through a combination of HLA-G, HLA-E, and classical HLA-class I tumour expression and numbers of tumour-infiltrating immune cells expressing FoxP3." (PMID 34361031, 2021). "Noteworthy, it has been repeatedly demonstrated that tumour HLA-G expression correlated with immune-related parameters in GC patients." (PMID 34361031, 2021). "Tumor expression of HLA-G can be further induced using low-dose chemotherapy, which when combined with anti-HLA-G CAR-NK results in extensive tumor ablation both in vitro and in vivo." (PMID 34663641, 2021). "The expression of HLA-G, an immune tolerant and tumor promoting factor, has been extensively investigated, and its role as a novel immune checkpoint has been established." (PMID 34054869, 2021). "In this way, potential patterns between HLA-G expression and tumour development in carcinoma patients were uncovered." (PMID 34361031, 2021). "The H scores of HLA-G in these tumor sections (average 133~152) were significantly higher than those in their paired adjacent tissues (average 1.2~17)." (PMID 34663641, 2021). "What is the relation between HLA-G expression and other factors involved in tumour progression such as HLA-class I downregulation and the presence of infiltrating immune cells?" (PMID 34361031, 2021). "Yet, considerable differences in tumour samples having high HLA-G expression were declared between these two studies (33% with 4H84 vs. 50% with MEM-G/2)." (PMID 34361031, 2021). "We conclude that, before any therapeutic application can be applied that targets HLA-G, more information is needed on tumour expression of HLA-G and of its isoforms." (PMID 34361031, 2021). "This includes the methods and types of analyses that were used to determine tumour HLA-G expression and its clinical impact." (PMID 34361031, 2021). "The results were consistent with previous studies that the intertumoral and intratumoral heterogeneity of HLA-G expression was commonly seen across different tumor types." (PMID 34276642, 2021). "On the other hand, tolerogenic DCs produce CD8+CD28+ and CD4+CD25+CTLA-4+ Tregs under the induction of HLA-G, which further strengthens the ability of immune escape of tumor cells." (PMID 34868081, 2021). "The anti-HLA-G construct switches the NK-inhibitory HLA-G signal to an activation signal that induces a cytotoxic killing response in NK cells engaged with target tumor cells." (PMID 34663641, 2021). "In a cohort of 136 primary cervical cancers, inter-tumor heterogeneity of the HLA-G expression was detected in 25% of these lesions and 11% of case-matched lymph node (LN) metastases." (PMID 34276691, 2021). "For instance, release of soluble HLA-G by tumor cells up-regulates CTLA-4, PD-1, TIM-3, and CD95 on CD8 T cells impacting their anti-tumor activity." (PMID 34447383, 2021). "As a result, the choice for the cut-off value at which patients were considered to have HLA-G-positive tumours, and thus the choice for which patient groups were compared with each other, was different between these studies." (PMID 34361031, 2021).
tumor (continued). "Aberrant expression of HLA-G and its soluble forms is considered to support tumor immune escape and often correlates with adverse clinical courses." (PMID 35095919, 2021). "Recent studies have found that tumor cells, cytotrophoblast cells, and mesenchymal stem cells can secrete HLA-G-carrying EVs, playing a role in regulating the tumor microenvironment and immunosuppressive function." (PMID 34868081, 2021). "HLA-G and PD-L1 inhibit different populations of T cells in cancer, and therefore critically contribute to tumor escape from immunosurveillance." (PMID 34938293, 2021). "Another shared function between CTBs and tumor cells is the expression of immune inhibitory molecules, including HLA-G and PD-L1." (PMID 34121116, 2021). "These include IL-6, IL-8 and TNF-α as well as the immune suppressive cytokines IL-10 and TGF-β, which increase HLA-G expression on tumor cells resulting in promotion of evasion from immune cells." (PMID 35111159, 2021). "Clear examples are the expression of HLA-G on trophoblast cells of the developing fetus during pregnancy or the enhanced expression of HLA-G on tumor or tumor-accessory cells contributing to immune evasion in cancer." (PMID 34295330, 2021). "Researchers have revealed that the expression of HLA-G in ascites, saliva, and bronchial lavage fluid can be useful for tumor diagnosis and prognosis." (PMID 34868081, 2021). "Especially, upregulated expression of HLA-G by tumor cells profoundly affected tumour-specific T cell immunity in the tumor microenvironment." (PMID 34276642, 2021). "On the one hand, this provides the most complete picture of the total HLA-G expression in the tumour lesion." (PMID 34361031, 2021). "In humans, we have widely studied the relationship between HLA-G expression and clinical outcomes in different tumor types, including solid tumors and hematologic malignancies." (PMID 34276642, 2021). "At the protein level, enhanced HLA-G expression has been found to be greatly correlated with weak anti-tumor immune response, disease progression, and poor survival, and HLA-G is an independent prognostic predictor of CRC." (PMID 34054869, 2021). "It is most likely that the differences in methodologies have contributed to the wide range in percentage of reported HLA-G-positive tumour samples, ranging from 24 to 62%." (PMID 34361031, 2021). "In tumor coculture assays, the anti-HLA-G scFv moiety promotes Syk/Zap70 activation of NK cells, suggesting reversal of the HLA-G-mediated immunosuppression and hence restoration of native NK cytolytic functions." (PMID 34663641, 2021). "Both HLA-G and HLA-E are commonly overexpressed on tumor cells, and expression is inducible by inflammatory cytokines." (PMID 34201079, 2021). "Here, we provide the first evidence and propose possible mechanisms for chemotherapy-induced processing and transportation of HLA-G to the surface of tumor cells, which sensitize them to killing by HLA-G-specific CAR-NK cells." (PMID 34663641, 2021). "In recent decades, accumulating evidence has shown that HLA-G is a tumor biomarker that plays key roles in tumorigenesis, tumor cell proliferation, invasion and metastasis." (PMID 34276642, 2021). "Activated T cells and NK cells obtain membrane fragments containing functional HLA-G from HLA-G+ or tumor cells through the process of exocytosis." (PMID 34868081, 2021). "Studies showing significant associations between HLA-G and poor clinical patient outcome also found positive correlations between HLA-G expression and tumour grade, stage, depth and LNM." (PMID 34361031, 2021). "Published works describe that HLA-G possesses a key role in the cancer immunoediting mechanism, attenuating the elimination of tumor cells." (PMID 34557189, 2021). "Another factor that should be highlighted in combination with HLA-G expression in tumours is the presence of infiltrating immune cells." (PMID 34361031, 2021).
tumor (continued). "Recent data showed that expression of HLA-G on tumor cells can be regulated by the transcription factor hypoxia-inducible factor 1α (HIF-1α) and that HIF-1α regulates MDSC function during murine pregnancy." (PMID 35111157, 2021). "The authors demonstrated that these cell lines as well as the isolated tumor cells possessed a trogocytotic capacity to capture membranes containing a immune-inhibitory molecule HLA-G from allogeneic sources." (PMID 33668117, 2021). "In this context, our findings in this study support the conclusion drawn from previous studies that tumor HLA-G expression is closely related to tumor progression and poor clinical outcomes in patients with cancer." (PMID 34054869, 2021). "In summary, we demonstrated for the first time that it is possible to block HLA-G expression in two different tumor cell lines through gene editing leading to its downregulation, with a concomitant effect in immune cell activation." (PMID 34773056, 2021). "Studies revealed that through the mechanism of trogocytosis action, T lymphocytes, activated NK cells, and monocytes can obtain HLA-G containing membrane fragments from HLA-G+ antigen-presenting cells or tumor cells." (PMID 33709198, 2021). "In a serial section study with colorectal and esophageal cancer lesions, our recent findings further revealed that intratumor heterogeneous expression of HLA-G is a very frequent phenomenon among different zones within a tumor." (PMID 34276691, 2021). "The differences in treatment history, tumor subtypes, and individual tumor microenvironment between different patients will also affect the evaluation of HLA-G expression levels." (PMID 34868081, 2021). "Noteworthy, only few studies on the intrapatient inter-tumor and intra-tumor heterogeneity of the HLA-G expression were available." (PMID 34276691, 2021). "Co-culture of NK with edited JEG-3/MIX-sgRNAs cells demonstrated that when the HLA-G expression disappears from the tumor cell surface, the NK cells partially recover their degranulation activity." (PMID 34773056, 2021). "They reported that patients with tumours showing strong staining for HLA-G expression had significantly better clinical outcome." (PMID 34361031, 2021). "HLA-G is involved in all three stages, and it is highly necessary to understand the role of HLA-G in tumor immune escape to better develop effective anti-tumor strategies." (PMID 34868081, 2021). "What stood out during the evaluation of these studies was the considerable discrepancy in HLA-G quantification methods and percentage of HLA-G-positive tumour samples." (PMID 34361031, 2021). "In this paper, we have used sgRNAs that target two genomic regions expected to affect the HLA-G translation in two different tumor cell lines." (PMID 34773056, 2021). "We generated several clonal cell lines with different HLA-G − degrees of downregulation, which constitutes a proof-of-concept study regarding the feasibility of knocking down the HLA-G gene in tumor cells." (PMID 34773056, 2021). "Especially in GC patients, correlations between tumour HLA-G expression and decreases in number of tumour-infiltrating NK and CD8+ cells and increases in number of Tregs were frequently observed." (PMID 34361031, 2021). "In consequence, determination of the panel of HLA-G isoforms expressed by tumor cells is severely limited and the implications of β2M-free HLA-G isoforms in the tumor immune escape mechanisms are misestimated." (PMID 32922387, 2020). "We agree that HLA-G is a potentially new immune checkpoint in cancer, but additional evidence is required to show the extent of intra-tumor and inter-tumor expression." (PMID 32630545, 2020). "Among the pool of inhibitory checkpoints shared between the placentation process and the tumor development, HLA-G is emerging as a potent immune escape mechanism." (PMID 32922387, 2020). "Studying all the functional aspects of HLA-G is essential in predicting how HLA-G-based immunotherapy will affect tumor growth." (PMID 33213057, 2020).
tumor (continued). "Probably, different ICs (e.g., PD-1, CTLA-4) and HLA-G influence each other as it has been reported, for instance, for TIM-3 expression on CD8+ tumor infiltrating lymphocytes that is closely associated with PD-1 expression." (PMID 32973812, 2020). "The lower survival rates were shown to be related to tumor cell infiltration in the lymph nodes and to the HLA-G expression." (PMID 32922387, 2020). "In this review, we will discuss how HLA-G expression is regulated under normal or abnormal conditions, and highlight the role of HLA-G played in tumor escape as well as the potential to target it for therapeutic benefit." (PMID 33425752, 2020). "Low oxygen increases HLA-G mRNA expression in trophoblasts and in tumor cell lines, but its effect on the expression of HLA-G protein is still undefined." (PMID 32733439, 2020). "HLA-G is involved in tumor progression, viral infection, organ transplantation, autoimmune and inflammatory diseases." (PMID 32023940, 2020). "Given that a high level of serum sHLA-G was frequently detected in patients with cancer, the importance of HLA-G in hampering the migration of NK and T cells into tumor microenvironment is becoming increasingly appreciated." (PMID 33425752, 2020). "Due to the role of HLA-G in tumor immune escape, it is proposed to be an immune checkpoint (IC) molecule." (PMID 32973812, 2020). "Earlier study found elevated expression of HLA-G and IL-10 in tumour sites and low levels of soluble HLA-G in saliva samples in OSCC17." (PMID 32123232, 2020). "Most likely, the tumor microenvironment plays a vital role in the induction of HLA-G and investigation of the specific mechanisms of differential HLA-G expression are highly important." (PMID 32560316, 2020). "Functionally, HLA-G has comprehensive immunosuppressive properties exerted in multiple steps to weaken anti-tumor immune responses by acting on immune cells through its inhibitory receptors: ILT2(CD85j/LILRB1), ILT4(CD85d/LILRB2), and KIR2DL4(CD158d)." (PMID 32670296, 2020). "In NHL, classical MHC molecules and HLA-G expression patterns were shown to be completely altered and correlated to a tumor relapse or transformation." (PMID 32922387, 2020). "Altogether, our results support that reversal of methylation-mediated repression of HLA-G is a co-acting mechanism by which tumor cells can take advantage of in order to avoid immune recognition." (PMID 32560316, 2020). "Previous studies analyzed the HLA-G and the HLA-E expression as well as the tumor infiltrating immune cell composition in a large cohort of RCC lesions using a TMA." (PMID 32993793, 2020). "This suggests that RNAi can be used to reduce HLA-G expression on tumor cells and, subsequently, inhibit its tumor-promoting effects." (PMID 33213057, 2020). "It was determined that HLA-G expression was detected in 64% of the tumor samples in the primary site of the carcinoma but HLA-G expression was absent in the surrounding tissue, evidencing HLA-G as a malignant transformation marker." (PMID 32922387, 2020). "HLA-G is a well-known immune checkpoint molecule involved in fetal-maternal tolerance and in tumor immune escape." (PMID 33505397, 2020). "Although most of HLA-G immunosuppression function and role in tumor escape studies were performed in vitro, HLA-G involvement in tumor escape mechanism was studied and demonstrated in vivo in immunocompetent mice through the induction of MDSC." (PMID 32922387, 2020). "This is partially explained by the fact that HLA-G is thought to suppress the cytotoxic activity of human NK cells against HLA-G-positive tumor cells via KIR2DL4 or other receptors, such as CD85j, CD85d, CD8, and CD160." (PMID 32023940, 2020). "HLA-G transcription is induced upon heat shock in tumor cell lines, via the heat shock transcription factor 1; however, the consequent HLA-G protein expression has not been investigated." (PMID 32733439, 2020).
tumor (continued). "Of the HLA class Ib molecules, HLA-G is probably the most studied in terms of cancer immunology and the most well-defined immunosuppressive molecule of the HLAs favoring tumor immune escape." (PMID 32560316, 2020). "As PD-L1 and HLA-G, both can be expressed by tumor cells, it would be interesting to evaluate how different phases of cell cycle affect the expression of these two proteins." (PMID 32961872, 2020). "The expression of HLA-G in tumor lesions should also be taken into consideration in the design of therapeutic strategies." (PMID 32560316, 2020). "Inter-tumor HLA-G expression in various types of tumor tissues has been widely investigated and its clinical significance has been well acknowledged." (PMID 33329527, 2020). "The expression of HLA-G in neoplasms was first identified in choriocarcinomas, neoplastic trophoblastic cells, and secondly identified in malignant melanoma." (PMID 32023940, 2020). "Since the HLA-G expression level is higher in CC (48%) than in CIN (27%), it was suggested that HLA-G expression was correlated to the tumor development." (PMID 32922387, 2020). "Because HLA-G is found on tumor cells and is rarely observed in healthy tissue, it appears to be an excellent tumor associated-antigen (TAA) to target in immune therapy." (PMID 32922387, 2020). "These anti-HLA-G CAR-T cells would target directly and specifically the HLA-G expressing cells to eliminate the tumor." (PMID 32922387, 2020). "HLA-G can be detected either on the cell-surface of tumor cells or on tumor infiltrating cells (TILs) particularly on lymphocytes, monocytes, macrophages and dendritic cells (DCs)." (PMID 32922387, 2020). "HLA-G expression was significantly correlated with tumor size, nodal status, and clinical disease stage.Patients with positive HLA-G expression had a lower survival rate than those with negative expression." (PMID 33425752, 2020). "Tumor cells typically downregulate HLA-I to evade the T cell immune response and, in parallel, they variably upregulate HLA-G to abrogate, at least in part, compensatory NK cell cytotoxicity." (PMID 32155826, 2020). "As a new immune checkpoint, the inter-tumor heterogeneous pattern of HLA-G expression is well evidenced; however, information for the intratumor heterogeneity of HLA-G is very limited." (PMID 33329527, 2020). "In vitro studies have shown that GM-CSF and IFN-γ secreted by the infiltrating cytotoxic T cells can enhance HLA-G expression in tumor cells." (PMID 33425752, 2020). "As we are now recognizing, HLA-G influences almost every stage of antitumor immune responses, such as T cell priming by DCs, and infiltration and function of effector cells at tumor." (PMID 33425752, 2020). "HLA-G has comprehensive immunosuppressive properties that are exerted in multiple steps to weaken the anti-tumor immune responses by acting on immune cells through its inhibitory receptors." (PMID 32670296, 2020). "A series of in vitro studies using tumor models have investigated the effect of these microenvironmental factors on HLA-G expression of tumor cells." (PMID 33425752, 2020). "The concentration of IFN-γ in patients are often lower in both peripheral blood and in the tumor microenvironment than the concentration used in the present study that was chosen with the aim to boost HLA-G expression." (PMID 32560316, 2020). "This implies that depending on the stage of the tumor, different immunotherapies against HLA-G should be applied." (PMID 32922387, 2020). "In contrast, a pathological HLA-G expression was found in many solid and hematopoietic tumors with an inter-tumor and intratumoral heterogeneity." (PMID 32993793, 2020). "HLA-G has been reported to be abnormally expressed in many kinds of tumor tissues and has been detected in the plasma of cancer patients." (PMID 33193435, 2020).